REN (renin)
Diseases named in the same sentence as REN in open-access papers (continued):
Sharing a sentence is not in itself a finding about the gene and the disease.
kidney damage (89 papers, 2009 to 2026). "The imbalance between the enzymes of the renin-angiotensin system reflects an alteration associated with stress induced by MS, generating an environment conducive to kidney damage, partially mediated by oxidative stress." (PMID 41226547, 2025). "OSA also causes activation of the sympathetic nervous system and renin-angiotensin-aldosterone system, leading to increased blood pressure and renal vasoconstriction, which can further exacerbate kidney damage." (PMID 37629482, 2023). "The effects include the modulation of renin release, calcium and phosphorus balance, excessive LPS, and kidney damage caused by a variety of acute and chronic diseases." (PMID 36145144, 2022). "Reduced BP was associated with increased plasma renin and markers of kidney damage (mice) in SCD, as well as significantly decreased plasma ACE concentrations and ACE enzyme activity." (PMID 35113975, 2022). "Increased blood pressure is associated with increased risk of kidney damage and cardiovascular disease, which challenges the explanation for a positive effect of renin production following GLP‐1RA treatment." (PMID 34277961, 2021). "Even with widespread use of renin–angiotensin system blockers and tight glycemic control, a substantial residual risk of nephropathy progression remains." (PMID 33222693, 2020). "Acid retention has been proposed to activate the intracellular renin-angiotensin system, through the previous stimulation of aldosterone production, which might be implicated in the onset or progression of kidney damage." (PMID 36245494, 2022). "The renin-angiotensin-aldosterone system has been implicated in progressive renal sclerosis, with recent evidence indicating that not only angiotensin but also aldosterone contributes to the progression of kidney damage by promoting thrombosis and fibrosis." (PMID 36006335, 2022). "Elevated intrarenal activity of the renin-angiotensin system may be an important determinant of sodium retention and BP as well as kidney damage, and this effect may be associated with increased tubular SGLT2 expression." (PMID 31375080, 2019). "Aged SHR may differ from that of adult SHR for their regulation of renin-angiotensin-aldosterone system associated with advanced kidney damage although renin-angiotensin concentrations remain unaffected." (PMID 25442699, 2014). "Dehydration may lead to elevated blood pressure, functional burden, oxidative stress, and inflammatory responses in the kidney, ultimately causing proteinuria and kidney damage, through the activation of the renin–angiotensin–aldosterone system and release of vasopressin." (PMID 39458467, 2024). "Following docking of fibroblast growth factor, the respective receptor increases the production of angiotensin-converting enzyme, which may in turn activate the renin–angiotensin system, potentially facilitating the onset and progression of kidney damage in high-risk individuals." (PMID 31533650, 2019). "Sympathetic stimulation causes elevated glucocorticoid levels and concurrent activation of the renin-angiotensin-aldosterone system, playing a critical role in the pathogenesis of kidney damage." (PMID 40576729, 2025). "Renal hypoperfusion secondary to kidney damage releases renin, which activates the renin–angiotensin–aldosterone system and increases arterial tension." (PMID 39063619, 2024). "Despite the implementation of the clinical use of renin–angiotensin aldosterone system (RAAS) inhibitors, gliflozins, endothelin receptor antagonists, and their combination, the kidney damage associated with AH is far from being resolved." (PMID 37298378, 2023). "Many factors, including hyperactivity of ACE and renin in the renin-angiotensin system (RAS), atrial and brain natriuretic peptides, cyclooxygenase-1 (COX-1), and calmodulin phosphodiesterase 1, are linked to kidney damage." (PMID 36985395, 2023).
kidney damage (continued). "Currently, the treatment for DN is multiple, including antihyperglycemic drugs, lipid-lowering agents, renin–angiotensin–aldosterone system inhibitors (RAASi), and pharmacological alternatives for nephropathy." (PMID 37248536, 2023). "In our DOX-induced nephropathy mouse model, we observed elevated expression of fPRR and sPRR proteins, increased sPRR levels, renal renin activity, and urinary Ang II excretion." (PMID 37841924, 2023). "It was postulated that deregulated renin‐angiotensin‐aldosterone system promotes increased burden of oxidative stress and inflammation, resulting in telomere length shortening and kidney damage." (PMID 37232505, 2023). "A more advanced T1DM model would introduce cofounding effects relating to nephropathy, such as renin–angiotensin–aldosterone system (RAAS) activation, and would not easily provide insight into the mechanism unpinning any changes to PN." (PMID 36644793, 2023). "On one hand, cardiac dysfunction can increase intrarenal resistance and decrease renal blood perfusion, which further aggravates kidney damage by activating the renin-angiotensin system, increasing inflammatory responses and oxidative stress." (PMID 35321107, 2022). "The increase in ALPK1, mainly in diabetic animal and human kidney cell models, leads to accelerated fibrotic nephropathy by enhancing the production of renin, TGF-β1, and IL-1β." (PMID 36139553, 2022). "In mice, glutamate inhibits the fusion of podocytes with ADR, nephropathy, cell apoptosis, renin expression and reduces urine albumin." (PMID 34938183, 2021). "Meanwhile, inhibition of renin expression with a vitamin D3 analog counteracted the increase in contrast-induced nephropathy induced by the ARB losartan in a rat model of CIAKI." (PMID 32241961, 2020). "Reducing glomerular pressure by blocking the RAA (renin–angiotensin–aldosterone) system alleviates proteinuria, and is considered a fundamental part of nephroprotection in nephropathies with proteinuria." (PMID 31108972, 2019). "In the kidney, angiotensin II (Ang II) is formed by independent mechanisms, and activity of the intrarenal renin–angiotensin–aldosterone (RAAS) system contributes to the progression of kidney damage." (PMID 27853882, 2017). "These cardiovascular risk factors contribute to kidney damage through various mechanisms, including increased insulin resistance, inflammation, oxidative stress and renin-angiotensin-aldosterone system activation, which in turn can promote the development of kidney damage in young adults." (PMID 37055746, 2023). "Second, higher sympathetic and renin-angiotensin-system activities were found in obese patients, which could enhance kidney damage." (PMID 35911764, 2022). "Overactivity of renin-angiotensin due to nephropathy may enhance reabsorption of sodium at the proximal tubule." (PMID 23777729, 2013). "The use of diuretics may resolve congestion and ameliorate global tissue perfusion and function, although over-diuresis could promote kidney hypoperfusion; drugs working on the renin–angiotensin–aldosterone system, such as ACEi, can further contribute to kidney damage." (PMID 40509072, 2025). "Evidence shows that poor sleep quality may lead to sympathetic nerve stimulation, thereby adversely affecting renal hemodynamics and blood pressure, reducing plasma renin activity, and leading to an imbalance of aldosterone regulation, which can lead to kidney damage." (PMID 35361150, 2022). "However, epidemiological investigations showed that merely a percentage of diabetic patients developed nephropathy despite optimal therapy including adjustment of blood glucose, blood pressure and blockade of the renin-angiotensin-aldosterone system using ACEIs and ARBs." (PMID 22900035, 2012).
kidney damage (continued). "Studies have shown that renin-angiotensin system may play an important role in the development of nephropathy in type II DM, and thus, the angiotensin converting enzyme (ACE) polymorphism may be a potential predictor for development of nephropathy in type II DM." (PMID 20535249, 2009). "Beyond its role in reducing the impact of the sympathetic nervous system on renal vascular resistance, renin release, and sodium reabsorption, recent studies have also shown that RDN can prevent T cell infiltration and subsequent kidney damage." (PMID 41189736, 2025). "This inadequate renal perfusion triggers baroreceptors, renin release, and activation of the renin-angiotensin-aldosterone system (RAAS), leading to kidney damage." (PMID 39829038, 2025). "Renin—angiotensin system (RAS) regulates the arterial blood pressure at both levels—systemic and tissue, and contributes to the immunological responses arising during various phases of nephropathy evolution." (PMID 30618805, 2018). "There is evidence of puromycin-induced RAS activation in nephropathy; however, intrarenal renin expression did not change in the present model." (PMID 25823676, 2015). "Although C57BL/6 J mice are relatively resistant to kidney damage, they have an advantage over other mouse strains in that, similarly to humans, they carry only one renin gene and do not develop glomerulosclerosis upon unilateral nephrectomy as other strains with two active copies of the gene do." (PMID 37111431, 2023). "Other authors have observed the involvement of the renin-angiotensin-aldosterone system (RAAS) and its complement in the pathogenesis of virus-induced kidney damage, thus hypothesizing that the pharmacological inhibition of RAAS and its complement may prevent kidney impairment." (PMID 36294442, 2022). "It is of significance to note here that a recent Interventional study aimed at blockade of the renin-angiotensin system (RAS) with ACE-inhibitors or ARBs, in patients with type 1 diabetes, did not slow nephropathy progression." (PMID 23028588, 2012). "Accordingly, higher urinary excretion levels of AGT and renin might be unique ADPKD features that are not simply a consequence of elevated plasma RAAS concentrations and renal function decline, but might be contributors to kidney damage." (PMID 38027263, 2023).
myocardial infarction (86 papers, 2007 to 2026). Gross necrosis of the myocardium, as a result of interruption of the blood supply to the area, as in coronary thrombosis. "The published literature offers a mechanistic explanation for the observed association between blood pressure and vitamin D. The renin-angiotensin system has been implicated in the regulation of BP levels as well as the risk of heart attack and stroke." (PMID 31434350, 2019). "Activation of the renin-angiotensin system (RAS) has been implicated in the pathogenesis of acute myocardial infarction (AMI)." (PMID 24086569, 2013). "This already suggests renal side effects caused by myocardial infarction leading to dysregulation of renin release." (PMID 24288471, 2013). "A variety of causes including myocardial infarction can increase renin release." (PMID 36689154, 2023). "Furthermore, the study revealed a lower risk of myocardial infarction among patients treated with inhibitors of the renin–angiotensin system." (PMID 37892676, 2023). "Damaged kidneys may release too much renin, which helps to control blood pressure but increases the risk for heart attack, congestive heart failure (CHF), and stroke." (PMID 31821152, 2019). "The progression of myocardial infarction (MI) was closely associated with the activation of the renin-angiotensin system (RAS)." (PMID 29184499, 2017). "Myocardial infarction initiates complex remodeling processes involving the renin-angiotensin system, through activation of the angiotensin II type 1 receptor (AT1R)." (PMID 42123578, 2026). "In acute myocardial infarction, the fall in sodium concentrations is closely related to activation of the sympathetic nervous system and the renin–angiotensin–aldosterone system, together with neurohormone-mediated, non-osmotic release of vasopressin." (PMID 41597514, 2026). "It is also known that, following an acute myocardial infarction, the arginine–vasopressin system as the renin–angiotensin and the sympathetic nervous systems, is activated." (PMID 36674841, 2023). "Examples of potential connections include the acute hemodynamic effects of myocardial infarction, the toxic effects of iodinated contrast media used for coronary angiography and drugs that modify the renin-angiotensin-aldosterone system." (PMID 27907067, 2016). "By the fourth LV, most variance was captured in having myocardial infarction in medical history (19%), and using agents acting on the renin-angiotensin system (C09; 14%), and beta-blocking agents (C07; 10%)." (PMID 26901048, 2016). "Left ventricular remodeling following acute myocardial infarction was also shown to be suppressed by decrease in MMP-9 level via inhibition of the renin-angiotensin system." (PMID 26551785, 2015). "Although the production of cardiac renin is debatable, mast cells constitute a major source of renin after myocardial infarction, contributing to the formation of local angiotensin II." (PMID 26078807, 2015). "Although renin uptake from plasma is an important source of cardiac renin, a renin transcript located exclusively intracellularly and overexpressed during myocardial infarct in rats indicates a role for cytosolic renin in post-ischemic repair processes." (PMID 25657639, 2014). "Concerning the origin of cardiac renin, evidence is available that in the normal heart, cardiac renin is dependent on its uptake from plasma but studies performed after myocardial infarction or after stretch of cardiomyocytes showed increased renin expression." (PMID 24600438, 2014). "ACE2 is upregulated in rodents and humans in macrophages, endothelial cells, smooth muscle cells, and myocytes following myocardial infarction which may restore renin-angiotensin-aldosterone system (RAAS) homeostasis in the heart post-MI." (PMID 39649442, 2024).
myocardial infarction (continued). "Here, we compared fibroblast activation in early HFpEF (cardiometabolic two-hit model), renin–angiotensin–aldosterone system activation-induced HFrEF (AngII model), early and later ischemic HFrEF (myocardial infarction model) to identify common fibroblast phenotypes across models." (PMID 39311911, 2024). "However, the renin-angiotensin-aldosterone system can increase the frequency of circulating monocytes by stimulating the release of monocytes from the spleen after myocardial infarction." (PMID 36778208, 2023). "Renin-angiotensin-system inhibitors (RASi) have shown survival benefits after acute myocardial infarction (MI), but the role of routine long-term use of RASi remains unclear." (PMID 36119742, 2022). "We also found that there is higher occurrence rate of acute myocardial infarction and severe coronary artery stenosis, yet lower rate of invasive revascularization intervention, lower medication rate of renin-angiotensin blocker in elderly coronary artery disease patients with renal insufficiency." (PMID 34606471, 2021). "Apart from the introduction of statin therapy, other changes in the last 30 years to prevent cardiovascular episodes include more widespread use of aspirin, antiplatelet therapy, and β-blockers for patients with previous myocardial infarction as well as inhibitors of the renin-angiotensin system." (PMID 30977858, 2019). "Moreover, the increased wall stress after myocardial infarction and increased plasma norepinephrine level result in the activation of the renin-angiotensin-aldosteron system (RAAS) followed by an increase of the renin and angiotensin II plasma levels." (PMID 24206753, 2013). "Interestingly, myocardial infarction increases the renal expression of this cotransporter that results in depolarization of renin-secreting cells and reduction of renin release." (PMID 24288471, 2013). "Since the expression of exon(1A-9)renin is selectively up-regulated after myocardial infarction, intracellular renin may play a role in the pathophysiology of ischemia-related repair processes." (PMID 18782187, 2008). "The renin-angiotensin-aldosterone system (RAAS) is involved in the cardiovascular homeostasis as shown by previous studies reporting a positive association between specific RAAS genotypes and an increased risk of myocardial infarction." (PMID 17519002, 2007). "Given the transgenic upregulation of renin and subsequently aldosterone in this animal model, we were keen to investigate the specific actions of mineralocorticoid receptor antagonism, utilising a clinically relevant dose of spironolactone in hypertensive animals subjected to myocardial infarction." (PMID 34843581, 2021). "The renin-angiotensin system (RAS) plays a pivotal role in the pathophysiology of myocardial infarction (MI), and in the development of heart failure." (PMID 24991808, 2014). "Furthermore, a renin transcript that does not encode a secretory signal and remains inside the cell is over-expressed during myocardial infarction suggesting that intracellular renin has functional properties." (PMID 24600438, 2014). "The presence of a renin transcript that does not encode a secretory signal and is over-expressed during myocardial infarction, raises the possibility that intracellular renin has an important role in the regulation of heart cell volume which is relevant during myocardial ischemia." (PMID 20066151, 2009). "Overall, sympathetic activation and the resulting elevated levels of renin, angiotensin, cortisol, serotonin, and free radicals can result in serious clinical outcomes like cardiac arrhythmias, myocardial infarction (MI), sudden cardiac death (SCD), and QT prolongation." (PMID 40943142, 2025). "The renin–angiotensin system (RAS) plays an important role in the development of hypertension and is also associated with the pathogenesis and progression of atherosclerosis, leading to cardiovascular (CV) disease such as myocardial infarction (MI)." (PMID 36893150, 2023).
myocardial infarction (continued). "The renin–angiotensin system is known to be stimulated after myocardial infarction (MI)." (PMID 34884604, 2021). "The renin-angiotensin-aldosterone system (RAAS) blockade is unequivocally established as the first and foremost clinically beneficial strategy in post-myocardial infarction (MI) and heart failure (HF) therapies." (PMID 34443591, 2021). "The renin-angiotensin system (RAS) is a major pathway in cardiac fibrosis and myocardial infarction (MI)." (PMID 28091615, 2017). "The renin-angiotensin-aldosterone system (RAAS) and sympathetic nervous system (SNS) activate in order to restore lost cardiac output following cardiac injury, such as myocardial infarction (MI) (1, –3)." (PMID 33500351, 2021). "In the heart, emerging evidence has revealed that renin transcript codes for exon (1A-9) renin (non-secreting intracellular renin; ns-renin), which is derived from alternative renin transcript, is increased by myocardial infarction." (PMID 29295576, 2017). "In addition, a transcript of non-secretory renin, which remains inside the heart cell is overexpressed during myocardial infarction." (PMID 25657639, 2014). "It remains to be elucidated whether cardiac downregulation of IGFII/M6P receptors as found in the early response to myocardial infarction is sufficient to reduce IGFII degradation and whether the same mechanism participates to the regulation of tissue-specific renin levels." (PMID 24288471, 2013).